G3BP2 (G3BP stress granule assembly factor 2)
Description:
Scaffold protein that plays an essential role in cytoplasmic stress granule formation which acts as a platform for antiviral signaling. Plays an essential role in stress granule formation. Stress granules are membraneless compartments that store mRNAs and proteins, such as stalled translation pre-initiation complexes, in response to stress. Promotes formation of stress granules phase-separated membraneless compartment by undergoing liquid-liquid phase separation (LLPS) upon unfolded RNA-binding: functions as a molecular switch that triggers RNA-dependent LLPS in response to a rise in intracellular free RNA concentrations (By similarity).
Synonyms: KIAA0660
Tractability: PROTAC: UniProt records ubiquitination sites on it; ubiquitination databases record sites on it; its protein half-life has been measured.
Gene: Protein-coding gene on chromosome 4 (75,641,849 to 75,726,301, reverse strand). Ensembl gene ENSG00000138757.
Subcellular location: Cytoplasm; Cytoplasm, Stress granule
Subcellular location (Human Protein Atlas): Cytosol
Pathways (Reactome):
Disease: SARS-CoV-2 activates/modulates innate and adaptive immune responses
Gene Ontology:
Molecular function: molecular condensate scaffold activity; protein binding; RNA binding; nucleic acid binding
Biological process: protein homooligomerization; stress granule assembly; membraneless organelle assembly; negative regulation of stress granule assembly; positive regulation of stress granule assembly; protein deubiquitination
Cellular component: cytoplasm; cytoplasmic stress granule; cytosol
Genetic constraint (gnomAD): Loss-of-function variants: 6 observed, 11.48 expected, observed/expected ratio (o/e) 0.52, 90% interval 0.28 to 1.03. The upper end of that interval is the gene's LOEUF score, 1.03, which puts it in group 4 of 6, group 1 being the genes least tolerant of losing a copy. Missense variants: 111 observed, 205.02 expected, observed/expected ratio (o/e) 0.54, 90% interval 0.46 to 0.63. Synonymous variants: 57 observed, 62.83 expected, observed/expected ratio (o/e) 0.91, 90% interval 0.73 to 1.13.
Homologues: Orthologues: chimpanzee G3BP2 (100% identical), rabbit G3BP2 (100% identical), macaque G3BP2 (99% identical), dog G3BP2 (99% identical), mouse G3bp2 (98% identical), pig G3BP2 (98% identical), rat G3bp2 (98% identical), guinea pig G3BP2 (98% identical), tropical clawed frog g3bp2 (85% identical), zebrafish g3bp2a (74% identical), zebrafish g3bp2b (70% identical), Drosophila melanogaster rin (43% identical), and 1 more. Paralogues in human: G3BP1 (65% identical).
Diseases named in the same sentence as G3BP2 in open-access papers:
G3BP2 is named in the same sentence as 56 diseases in open-access papers, as found by Europe PMC text mining. Sharing a sentence is not in itself a finding about the gene and the disease. The quoted sentences say what the papers report.
prostate carcinoma (20 papers, 2018 to 2025). A carcinoma that arises from epithelial cells of the prostate gland. "Increased G3BP2 promoted the growth of cancer cells and high expression level of G3BP2 was associated with poor prognostic in Head and Neck squamous cell carcinoma, prostate cancer, breast, and lung cancer." (PMID 38735008, 2024). "We aimed at unveiling the potential of G3BP2 as a biomarker for osteosarcoma treatment which has been reported to be with high expression in cancer cells such on prostate cancer and BC." (PMID 35761386, 2022). "Meanwhile, TRIM25 and G3BP2 have previously been shown to interact in the context of prostate cancer." (PMID 36067236, 2022). "Therefore, it is not excluded that an unnoticed molecular plays a similar role to TSPYL5 in the nuclear membrane translocation of G3BP2 in prostate cancer cells." (PMID 40319028, 2025). "Our study aimed at investigating the function of G3BP stress granule assembly factor 2 (G3BP2), which is an oncogene for breast cancer (BC) and prostate cancer but remains unknown in osteosarcoma cells." (PMID 35761386, 2022). "For instance, G3BP2 could induce prostate cancer cell cycle progression and accelerate tumor growth, while block cell apoptosis." (PMID 35761386, 2022). "In addition to Caprin1, G3BP2 expression is an independent prognostic factor predicting poor outcome in prostate cancer." (PMID 31771591, 2019). "In prostate cancer cell lines SK1 knockdown (KD) has significantly changed expression of several genes including downregulation of NSUN2, G3BP2 and upregulation of ETS1." (PMID 30971929, 2019). "Notably, silencing of TRIM25 did not only diminish the cytoplasmic abundance of G3BP2 but also reduced total G3BP2 levels, suggesting a dual role of TRIM25 in both protein expression and subcellular localization of G3BP2 in prostate cancer cells." (PMID 39851496, 2025). "Moreover, we identified G3BP2 as an independent prognostic marker in HNSC, consistent with prior reports in prostate cancer, breast and lung cancer." (PMID 36878903, 2023).
breast carcinoma (14 papers, 2010 to 2026). "At the same time, exosomal circBACH1 enhances breast cancer cell stemness, angiogenesis, and metastasis by targeting the miR‐217/G3BP2 axis, thereby promoting paclitaxel resistance and advancing breast cancer progression." (PMID 39584047, 2024). "In breast cancer, G3BP2 regulates tumor initiation through the stabilization of SART3 (squamous cell carcinoma antigen recognized by T cells 3) mRNA." (PMID 35954483, 2022). "A recent study also confirmed that GTPase-activating protein (SH3 domain)-binding protein 2 (G3BP2) stabilized PD-L1 mRNA through its RNA recognition motif and upregulated PD-L1 expression under stress in breast cancer and GBM." (PMID 34088360, 2021). "To confirm these data, we checked for correlation between G3BP2 and PD‐L1 proteins in 47 patient samples representing different breast cancer subtypes and found that G3BP2 and PD‐L1 were positively correlated (overall R2 = 0.8–0.9, P < 0.0001)." (PMID 33525064, 2021). "We found that G3BP1 to a larger extent than G3BP2 influences mRNA expression levels and breast cancer cell proliferation." (PMID 24321297, 2013). "Another study found that G3BP2, one of the potential targets of miR-122a, was more highly expressed in breast cancer tissue than in paraneoplastic tissue." (PMID 21192833, 2010). "Our work aligns with emerging efforts to target SGs and post-translational modifications in cancer therapy, such as MPN-based SG inhibitors in hepatocellular carcinoma and G3BP2-targeted approaches in breast cancer, underscoring the translational potential of targeting stress response pathways." (PMID 41029457, 2025). "G3BP2 was an oncogene involved in breast cancer progression and metastasis." (PMID 37461019, 2023). "For example, the loss of G3BP2 has been shown to promote nuclear translocation of TWIST1 with increasing matrix stiffness to drive epithelial-mesenchymal transition (EMT) tumor invasion and metastasis in breast cancer." (PMID 34782720, 2022). "C108 repressed G3BP2 and downregulated PD-L1 expression in breast cancer and GBM." (PMID 34088360, 2021). "To determine whether our cell‐based data recapitulate the cancer features, we first examined the co‐expression of G3BP2 and PD‐L1 genes in 1109 patient tissues diagnosed with breast cancer from TCGA database." (PMID 33525064, 2021). "In conclusion, our study demonstrates specific effects of G3BP1 and G3BP2 in breast cancer cells." (PMID 24321297, 2013). "Additionally, G3BP2 could trigger tumor initiation in breast cancer via upregulation of Oct-4 and Nanog23." (PMID 37884630, 2023). "Hence, it is possible that the DDX3X protein could enhance the effect of G3BP2 in breast cancer and play an oncogenic role in tumor initiation." (PMID 35954483, 2022). "Five genes (DPH2 G3BP1, G3BP2, NSUN2, and TTC17) were similarly regulated by SK1 KD in prostate and breast cancer cells." (PMID 30971929, 2019). "Specifically, paclitaxel (PTX) promotes the release of exosomal circBACH1 in breast cancer cells, which contributes to drug resistance by reducing the levels of miR-217 and elevating the expression of GTPase-activating SH3 domain-binding protein 2 (G3BP2)." (PMID 41179289, 2025). "Here, we show that G3BP1, but not G3BP2, supports proliferation of several breast cancer cell lines." (PMID 24321297, 2013). "Thus, G3BP1, but not G3BP2, seems to be a proliferation-promoting factor in breast cancer cells." (PMID 24321297, 2013). "We could only see effects on proliferation following G3BP1 depletion and not upon G3BP2 depletion, indicating that G3BP1 and G3BP2 may have different functions in breast cancer cells." (PMID 24321297, 2013).
viral infection (11 papers, 2014 to 2026). "G3BP2, a key component of stress granules, is implicated in viral infection, while ZNFX1 is essential for initiating the type I interferon (IFN) response." (PMID 40783707, 2025). "Our data agree with a recent report showing that knocking out both G3BP1 and G3BP2 is required for SG inhibition during viral infections." (PMID 37983241, 2023). "On the other hand, G3BP1 and G3BP2 had antiviral activity against poliovirus (PV) and alphaviruses, suggesting a variety of possible mechanisms of action in viral infections." (PMID 24992036, 2014). "Immunofluorescence analysis further supported the hypothesis that G3BP2 increasingly binds to STAT1 in the cytoplasm during virus infection." (PMID 40626722, 2025). "G3BP2 is essential for the assembly of stress granules (SGs), which provide a way for eukaryotic cells to respond to various sources of stress, such as oxidative conditions, heat shock, ultraviolet light, and viral infection, by forming cytoplasmic components." (PMID 40076950, 2025). "Additionally, G3BP2 is closely associated with various non-tumor diseases, including viral infections, as well as cardiovascular and cerebrovascular diseases." (PMID 41752399, 2026). "Compared with the cellular infection experiment, the protein expression of G3BP2 and TRIM25 increased gradually in the early stage of virus infection." (PMID 36560452, 2022). "The antiviral effect was not restricted to the laboratory adapted DENV-2 NGC as G3BP1, G3BP2 and CAPRIN1 had antiviral activity against the clinical DENV-2 isolate PR1940 as well as the related yellow fever vaccine strain (YFV-17D)." (PMID 24992036, 2014).
bladder cancer (6 papers, 2018 to 2023). "On the other hand, inhibition of G3BP2 suppressed bladder cancer progression by upregulating circFNDC3B to reduce miR-1178-3p and inhibit the downstream SRC/FAK signaling pathway." (PMID 37461019, 2023). "The circular RNA circFNDC3B reduces bladder cancer progression through the miR-1178-3p/G3BP2/SRC/FAK axis." (PMID 34322376, 2021). "Additionally, it has been verified that G3BP2, an oncogene for BC was negatively regulated by miRNA to inhibit osteosarcoma and bladder cancer progression." (PMID 37461019, 2023). "Moreover, circFNDC3B could repress oncogene G3BP2 via binding with miR-1178-3p, thus suppressing bladder cancer progression." (PMID 37884630, 2023). "Besides, circFNDC3B competitively binds to miR-1178-3p, resulting in decreased expression of G3BP2, and then inhibits the downstream SRC/FAK signaling pathway to impair tumor growth and lymphatic metastasis in bladder cancer." (PMID 34782720, 2022).
colorectal cancer (6 papers, 2023 to 2026). A primary or metastatic malignant neoplasm that affects the colon or rectum. "Another study indicated that G3BP2 could enhance radioresistance of colorectal cancer cells." (PMID 40783393, 2025).
non-small cell lung carcinoma (6 papers, 2021 to 2026). A group of at least three distinct histological types of lung cancer, including non-small cell squamous cell carcinoma, adenocarcinoma, and large cell carcinoma. "MG53 can promote the formation of SGs in non-small cell lung cancer by regulating the activity of G3BP2." (PMID 37179344, 2023). "In our early study, we found that MG53 suppresses tumor progression and stress granule formation by modulating G3BP2 activity in non-small cell lung cancer." (PMID 36147477, 2022). "Selective control of G3BP2/SG signaling is a potential means to treat non-small cell lung cancer (NSCLC)." (PMID 34521423, 2021).
breast tumor (5 papers, 2017 to 2024). "The loss of G3BP2 inhibits breast tumor initiation, possibly lead to improved cancer treatments." (PMID 39190284, 2024). "G3BP2 (G3BP Stress Granule Assembly Factor 2) regulates breast tumor initiation by stabilizing squamous cell carcinoma antigen recognized by T cells 3 (SART3) mRNA." (PMID 39190284, 2024). "In previous work, we found that G3BP2 protein was involved in stimulation of breast tumor‐initiating cells, acting through SART3 and the pluripotency transcription factors Oct‐4 and Nanog." (PMID 33525064, 2021). "In human breast tumours, collagen fibre alignment and reduced expression of G3BP2 together predict poor survival." (PMID 28544627, 2017). "The results show that colocalization of G3BP2 and PD‐L1 was higher in the stressed group than the nonstressed group, supporting the hypothesis that G3BP2 and PD‐L1 are co‐upregulated in breast tumors exposed to chemical stress." (PMID 33525064, 2021).
lung carcinoma (5 papers, 2021 to 2024). "Several previous studies have noted that G3BPs (G3BP1 and G3BP2) are upregulated and associated with poor prognosis in human cancers including gastric, breast, lung cancer, sarcoma, prostate, hepatic, and colon cancer." (PMID 34521423, 2021). "In summary, data from the current study characterized a novel function of MG53 in the modulation of G3BP2-mediated SGs associated with lung cancer tumorigenesis." (PMID 34521423, 2021). "We show that MG53, a member of the TRIM protein family (TRIM72), modulates G3BP2 activity to control lung cancer progression." (PMID 34521423, 2021). "Since the TRIM domain of MG53 contains the potential active motif(s) to facilitate interaction with G3BP2, targeting the TRIM/G3BP2 interaction can potentially be explored as alternative means to treat lung cancers." (PMID 34521423, 2021). "In an vivo study, inhibiting G3BP2 activity by knocking down MG53 significantly reduced tumor volume and weight in mouse lung cancer model, which suggests that targeting G3BP2 had a significant anticancer effect in NSCLC." (PMID 37179344, 2023).
gastric cancer (3 papers, 2021 to 2026). A primary or metastatic malignant neoplasm involving the stomach. "Effective blockade of STAT3 activity by the STAT3 inhibitor stattic sensitized gastric cancer cells to cisplatin and reduced expression of the cisplatin resistance‐related genes G3BP2, THOC1, ATP7A, and OTUD1." (PMID 34375503, 2021). "Effective blockade of the STAT3 activity by STAT3 inhibitor sensitized gastric cancer cells to cisplatin and reduced the cisplatin‐resistant‐related gene G3BP2, THOC1, ATP7A, and OTUD1 expression." (PMID 34375503, 2021). "By analysing microarray datasets from the Gene Expression Omnibus (GEO) and the Cancer Genome Atlas (TCGA) database, we found that the mRNA level of G3BP1, but not that of family member G3BP2, was significantly higher in human gastric cancer samples than in normal tissue samples." (PMID 32989225, 2021).
head and neck squamous cell carcinoma (3 papers, 2022 to 2025). A squamous cell carcinoma that arises from any of the following anatomic sites: lip and oral cavity, nasal cavity, paranasal sinuses, pharynx, larynx, and salivary glands. "USP7 and PRMT5-dependent G3BP2 stability drives de novo lipogenesis and tumorigenesis in head and neck squamous cell carcinoma." (PMID 39944823, 2025). "In addition to that in ESCC, we also detected the expression of G3BP2 in other types of squamous cell carcinoma, including lung squamous cell carcinoma (LUSC) and head and neck squamous cell carcinoma (HNSCC)." (PMID 34782720, 2022).
oral cancer (3 papers, 2020 to 2023). "The targeting of FOXD1 might be a good strategy to enhance the radiosensitivity of oral cancer cells via downregulating G3BP2-related pathways and upregulating the TXNIP-associated cellular functions." (PMID 32967107, 2020). "Similar to FOXD1, the mRNA levels of G3BP2 in HSC4 cells were higher than other oral cancer cell lines." (PMID 32967107, 2020). "In oral cancer cells, FOXD1 promotes the malignant progression of cells by upregulating G3BP2 expression via directly binding to its promoter." (PMID 37906341, 2023).